SOX2 (SRY-box transcription factor 2)
Diseases named in the same sentence as SOX2 in open-access papers (continued):
Sharing a sentence is not in itself a finding about the gene and the disease.
tumor (continued). "Additionally, SOX2 and OCT4 can synergize with HIF-1α to promote tumor cell migration and invasion." (PMID 39781344, 2025). "Indeed, the neuronal markers NeuN, neurofilament protein, and chromogranin were negative, and the tumor cells displayed mild positivity for SOX2 and focal immunoreactivity for synaptophysin." (PMID 39492623, 2025). "However, treatment with RIN-1, an inhibitor of the RBPJ subunit of the NOTCH complex, significantly decreased SOX2 expression in tumor cells, suggesting that SOX2 expression regulated by NOTCH signaling may contribute to tumor development." (PMID 40128799, 2025). "Second, due to the heterogenous nature of tumors different animals may have tumor subpopulations that do not rely on SOX2 and thus may survive treatment, leading to resistance." (PMID 39736115, 2025). "PTEN as a tumor suppressor impeded the self-renewal capacity and non-anchorage-dependent growth potential of LCSCs while diminishing the expression of stemness-associated genes, including CD44, ALDH1, Bmi1, Sox2, and Oct4, thus attenuating LCSC stemness." (PMID 40710326, 2025). "However, Sox2 knockdown failed to reduce Ki-67 expression in tumor cells with virus-mediated overexpression of LMX1A or LMX1B, suggesting that LMX1 transcription factors support NOTCH-driven CP tumor cell proliferation in the absence of SOX2." (PMID 40128799, 2025). "Although we did not isolate tumour cells to confirm stem cell characteristics, previous human pituitary studies have demonstrated such findings in association with immunopositivity for markers CD133, SOX2 and Nestin." (PMID 38483762, 2024). "The hyaluronan receptor CD44, which has also been proposed as a SLGC and GBM subtype marker with significance in tumor progression showed varying expression levels in Western blots, in which high CD44 expression was observed for both SLGC cultures with high and low Sox2 levels." (PMID 38306361, 2024). "Despite the fact that the absolute number of CD117+CD44+, CD117+EGF+ and CD117+EGF+CD44+ cells did not increase in tumor formation, the relative content of Sox2+ cells in these populations was significantly higher compared to similar indicators in intact animals." (PMID 38664641, 2024). "Overexpression of SOX2 and related aberrant interacts with various signaling pathways such as unchecked proliferation, apoptosis resistance, altered autophagy, enhanced EMT, and maintenance of CSCs, promoting tumor development, metastasis, and treatment resistance." (PMID 39170516, 2024). "The intricate network of TFs, including SOX2, OCT4, NANOG, KLF4, c-MYC,β-catenin, STAT3, NF-κB, HIF-1α and YAP/TAZ, is central to the maintenance of the stem-likeproperties of GSCs, which in turn drive tumor heterogeneity, therapeutic resistance, andrecurrence." (PMID 38716541, 2024). "Tumor cells with transferred astrocytic mitochondria showed higher proliferation capacity (bigger proportion of tumor cells in G2/M phase of cell cycle) and capability to self-renew (higher expression of SOX2 and OCT4) compared with GBM cells without mitochondria transfer." (PMID 38786032, 2024). "In comparison to adherent cells, the tumor spheroids thus generated showed an increased expression of stem markers, such as ALDH1A1, CD44, and CD133, and core transcription factors of the human stem cell pluripotency signaling pathway, such as Oct4, Sox2, and Nanog." (PMID 39335624, 2024). "We observed that tumor cells, irrespective of genotype, were SOX2+." (PMID 39609428, 2024). "However, other properties are typical of CSCs such as radio-resistance, self-renewal capacity, tumor-initiating capacity, invasiveness, tumor cell differentiation, and the expression of various molecules that support stemness such as OCT4, SOX2, and Nanog, among others." (PMID 38672378, 2024). "Of these two CD133 positive tumours, one co-expressed SOX2 and the other did not." (PMID 38483762, 2024).
tumor (continued). "qRT-PCR analysis of xenograft tumor samples showed that the ADAMTS9-AS2–overexpressing group had higher levels of differentiation markers (Syn and Tau) and lower levels of MYCN and stem cell markers (Nestin and SOX2) compared with SK-N-Be2 cell xenograft vehicle groups." (PMID 37991019, 2023). "However, β8-overexpressing, SOX2 promoter-GFP tumor cells (~1,100 Pa stiffness) could be converted to GFPhigh tumor cells in mice." (PMID 37614365, 2023). "In view of PKMYT1AR function in NSCLC, the authors also targeted it in vitro and in tumor xenografts, showing that its inhibition through ASOs can efficiently impair tumor stem features, as self-renewal, and the expression of stem cell markers, as CD44 and SOX2." (PMID 36768150, 2023). "Thus, to understand the biological correlations between 3D spheroid configurations and the tumor pathogenesis of MM in more detail, additional investigations with the objective of identifying additional unidentified factors related to KRAS and SOX2 will be our next projects." (PMID 36899895, 2023). "Tumor spheres originate from self-renewing cells and exhibit an augmented CSC phenotype along with an elevated expression of stemness transcription factors (Nanog, Oct4, KLF4, Lin28, and Sox2), in contrast to their corresponding monolayer adherent cell counterparts." (PMID 37759448, 2023). "Another explanation for these contradictory results may be that SOX2 expression is an early tumor-initiating event and is therefore important for tumor development but is not involved in conveying an aggressive or metastasizing phenotype." (PMID 37888115, 2023). "CSCs in these tumours were somewhat different, the markers of which were PLP, Nestin, P75, GAP43, and Sox10, with GFAP, S100, and GAP43 (as a Schwann cell marker) in differentiated cells, in neurofibroma and MPNST; and Oct4, SOX2, Nanog, MYC, KLF4, CD133, CD44, and CXCR4 in CSCs of schwannoma." (PMID 37370764, 2023). "In particular, we show for the first time that SOX2 is over-expressed not only in the tumor core but also in the close margin of OSCC patients with advanced tumor stage and lymph node compromise, thus suggesting that high levels of SOX2 may predict for a local spreading." (PMID 38096163, 2023). "Moreover, when the ZNF852 is knocked down using the CRISPR/cas9 system in GC, its ability to reproduce is inhibited, along with the decreased expression of Nanog, SRY-box 2 (Sox2) and Oct4, meaning that ZNF852 preserves the self-renewal and tumor stem cell properties of GC." (PMID 37174714, 2023). "Flow-cytometric analysis showed the presence of different pituitary lineages (which may originate from the tumor and/or adjacent tissue), as well as enrichment of the TBX19+ (corticotrope) lineage and stem cells (marked by SOX2, CXCR4 and CD133), similar to the patient’s tumor." (PMID 37614709, 2023). "Indeed, the co-expression of Oct4/Sox2 inhibits the expression of the C-C Motif Chemokine ligand 5 (CCL5) and C-X-C Motif Chemokine ligand 9, 10 and 11 (CXCL 9,10 and 11), which mediate CD8+ T cell attraction against tumor cells." (PMID 36831383, 2023). "Thus far, the changes in genes that enable SOX2 levels to rise in different cancers without blocking tumor growth have not been studied adequately." (PMID 35454854, 2022). "Recently, a cross-regulation of key EMT (SNAI2/Slug) and stemness (Sox2) genes have been reported, supporting the hypothesis that a stemness–EMT axis is operating and providing the necessary plasticity to guarantee the maintenance of tumor heterogeneity." (PMID 36499245, 2022). "Therefore, we sought to detect the expression of SOX2, CD44, and ALDH1A1 in CxSCC tumor buds." (PMID 35860042, 2022). "Our results show that PFKFB3-mediated targeting by PFK158 or genetic manipulation resulted in inhibition of glycolysis and of tumor progression, resulting in diminished cancer “stemness” by decreasing both surface and intracellular stem cell marker expressions such as CD133, CD44, Aldh1, and Sox2." (PMID 35804016, 2022).
tumor (continued). "Furthermore, regarding reduced tumor volume, tumor weight, and elevated tumor apoptosis rate, it was worthy to note that OCT4&SOX2 CTLs plus PD-1 inhibitor (nivolumab) showed better effects compared to PD-1 inhibitor (nivolumab) alone and OCT4&SOX2 CTLs alone." (PMID 35402219, 2022). "Having the difference in tumor frequency between the ubiquitous and promoter specific models suggests that there might also be other cells of origin, which do not express Sox2 during tumor initiation and thus cannot be detected by our Sox2-cre models." (PMID 35318328, 2022). "Pharmacologic HhAntag treatment resulted in about 35% tumor volume reduction after 2 weeks and a 32% decrease observed in the active nuclear form of YAP protein and also a significant decline in the protein level of stem cell marker SOX2 and survivin (a YAP down-stream effector)." (PMID 35501851, 2022). "Interestingly, SOX2+ tumor cells resided closer to the microvascular networks compared to SOX2‐ tumor cells regardless of the complexity of the perivascular culture." (PMID 36109186, 2022). "Thus, the activation of SOX2 (z = 2.39) predicted for the BOG in this study might imply that the overexpression of SOX2 restricts the growth of PDAC cells, while the endogenous intermedium levels of SOX2 lead to maximum tumor growth." (PMID 36038612, 2022). "Conversely, in 79 (90.8%) samples, the main tumor body showed negative/low expression of SOX2." (PMID 35860042, 2022). "Notably, DHCT treatment of HCC cells resulted in the reduced expression of α7nAChR, JAK2, and cancer stemness markers (CD133, KLF4, and SOX2) as well as decreased ALDH1 activity, thereby suppressing the colony-forming and tumor sphere generation abilities of HCC cells." (PMID 35111269, 2022). "Since the proliferative and tumor stemness phenotypes were significantly affected by FAM64A inhibition, we next detected markers reflecting proliferation and cancer stemness, and found that the levels of PCNA, CD44, SOX2, and BMI-1 were all markedly decreased upon reduction of FAM64A." (PMID 35538067, 2022). "Given that OCT4, SOX2 and NANOG are crucial to maintain stemness, we need a greater knowledge of the mechanisms that regulate the expression of these factors to design new therapeutic interventions that can eventually overcome issues such as chemotherapy resistance, tumor recurrence, and metastasis." (PMID 36118530, 2022). "However, the mechanisms through which elevated SOX2 levels inhibit tumor cell proliferation have not been identified." (PMID 35454854, 2022). "The tumor was negative for cytokeratins, p40, SOX2, and MYC and positive for NUT, FLI1, and CD99." (PMID 34898574, 2021). "Compared to 2D monolayers, there was a twofold increase in the expression of the stemness-related transcription factors SOX2 and KLF4 in PA-ECM cultures and a much higher proportion of CD133 + /CXCR4 + cells than in spheres or organoids, which falls in the range of matched PDX tumours." (PMID 34561461, 2021). "In the absence of OCT4 expression, neoplasms could not be initiated from normal tissues, but without SOX2 expression, the neoplastic cells could not be self-renewed to maintain tumor growth." (PMID 34201050, 2021). "In order to investigate whether BET inhibition affects the tumor-initiating ability of EPN SC cultures, we assessed the expression of previously defined neural cancer SC markers (PROM1, NES and SOX2) and of the astrocytic marker GFAP in the cells treated with OTX015." (PMID 33668642, 2021). "SOX2 peptide vaccine can significantly enhance systemic and local immune responses, and prolong the survival of tumor-bearing animals in tumor models, with definite efficacy observed regardless of whether combined with chemotherapy." (PMID 34630121, 2021).
tumor (continued). "SOX2 is responsible for some characteristics of cancer cells such as proliferation, epithelial–mesenchymal transition (EMT), migration, invasion, metastasis, spherical and colony formation, tumor initiation, cancer stem cell formation, and resistance to apoptosis and therapy." (PMID 35008527, 2021). "Expression of oncogenic β-catenin in SOX2 + ve cells of the postnatal pituitary, which contain bona fide organ-specific stem cells results in the initial formation of β-catenin-accumulating cell clusters and subsequent development of ACP-like tumours after a latency period of 3–6 months." (PMID 34019103, 2021). "Interestingly, four tumor samples harbor duplications of only the enhancer region without the SOX2 gene, reminiscent of our previous findings regarding duplications of MYC and KLF5 enhancers." (PMID 34880227, 2021). "For example, the lung cancer lineage specifiers SOX2 and NKX2-1 contribute to tumor cell fate and neutrophil recruitment, suggesting that the determination of tumor immune microenvironment might impact the nature of the tumor." (PMID 34497681, 2021). "The mean number of CD20+ TILs in both the tumor and the surrounding stroma was consistently higher in tumors harboring negative expression of SOX2 and NANOG, although this inverse relationship only reached statistical significance for the SOX2 marker (p = 0.008)." (PMID 33494389, 2021). "Given the fundamental role of SOX2, OCT4, and NANOG in supporting self-renewal properties, we examined their levels in tumors that appeared early, demonstrating enhanced tumor-initiation ability, versus those that appeared late, showing poor tumor-initiation ability." (PMID 33445692, 2021). "The administration of ODZ10117 dramatically decreased the tumor population and the levels of active STAT3, CSC markers such as NESTIN and SOX2, and MES-associated genes FN and ITGAV without significantly affecting the body weight compared to the vehicle-treated control group." (PMID 32183406, 2020). "Since SOX2 and BCL-2 could affect signaling pathways known to exert some sort of influence on OKC and AB, and since these two genes may interact with each other in other tumor models, the study of their expression in OKC and AB seems to be opportune." (PMID 31967981, 2020). "In parallel, SOX2 was found to cooperate with important oncogenes, like Wnt1 (OMIM: 164820), Wnt2 (OMIM: 147870), c‐Myc (OMIM: 190080), and Notch1 (OMIM: 190198), to promote lung tumor occurrence, while downregulation of SOX2 inhibited proliferation and induced apoptosis in tumor cells." (PMID 32130794, 2020). "Octamer transcription factor-3/4 (OCT3/4), SRY-box 2 (SOX2), Nanog and LIN28 are genes related to the tumor stem cell-like phenotype that have been proven to be related to TIE.106,107 ncRNAs can also promote the tumor stem cell-like phenotype by directly or indirectly regulating those genes." (PMID 32561709, 2020). "Specifically, it was not determined whether the inhibition of tumor growth by elevated SOX2 could be reversed by returning SOX2 to basal levels." (PMID 32998722, 2020). "It has also been shown that SOX2+ cells can differentiate in all hormone-producing cell types of pituitary in mice model and that SOX2+ cells with altered β-catenin expression contribute to tumor formation in a paracrine manner but do not constitute cells of the PA tissue mass." (PMID 32528411, 2020). "However, direct descent of tumor cells from SOX2+ cells was not supported in the Drd2-/- mouse using SOX2+ lineage tracing, thus questioning their role as TSC." (PMID 33584539, 2020).
tumor (continued). "SOX2 suppression by RNAi or abrogation of EGFR, Src, or Akt signaling through EGFR tyrosine kinase inhibitors Gefitinib, Erlotinib, or BIBW2992 or Src inhibitor Dasatinib could result in curbing stem-like properties and regrowth of tumor." (PMID 30517668, 2020). "Furthermore, for one of these tumor cell lines, i-SOX2-ONS76, we examined whether elevating SOX2 altered the cell cycle distribution at earlier time points." (PMID 32998722, 2020). "Furthermore, Nanog and SOX2 targets may be perturbed by the SOX10 family, suggesting the importance of SOX10 in activation of cells to the MIC state at the tumor periphery." (PMID 32620903, 2020). "Noteworthy, by immunohistochemical analysis, we also evaluated in tumors and preneoplastic lesions of Ptch1+/−/Btg1WT and Ptch1+/−/Btg1KO mice the expression of Sox2, a marker for tumor stem cells in Shh-induced MB, without finding any difference (data not shown)." (PMID 32231994, 2020). "Given the need to carefully control the levels of SOX2 in both normal and tumor cells, it is not surprising that SOX2 is regulated by a highly diverse set of regulatory mechanisms that control its transcription, translation, subcellular location, transcriptional activity, and stability." (PMID 32998722, 2020). "The idea to test ALDH and SOX2 markers derives from the consideration of the pathological characteristics of this tumor constituted by an abundant vascularized component, and for the roles that ALDH and SOX2 may have in the process of endothelial vascular tumor progression." (PMID 32984377, 2020). "In cancer, SOX2 expression frequently coincides with the CSC compartment from which tumorigenicity, therapy-resistance, and disease relapse are thought to arise, and moreover with circulating CSC islets as structural correlates of tumor dissemination and metastasis." (PMID 32664542, 2020). "Moreover, we found that FAK KD HepG2 and Huh-7 cells, but not macroH2A1 KD HepG2 and Huh-7 cells, displayed a simultaneous significant increase (p < 0.01) in the mRNA levels of cancer stemness suppressor genes GATA6, SMAD4, and BMP7, and of tumor-promoting genes KDR and SOX2." (PMID 33182805, 2020). "Moreover, SOX2 and SOX2OT expression levels were correlated with stage of tumor." (PMID 31956395, 2020). "It is likely that METTL3 promote the expression of SOX2 and MYC through m6A-based posttranscriptional regulation as well as AFF4-mediated regulation at the transcriptional level, which reinforces the signal activating the tumor-initiating and self-renewal capabilities of BCa cells." (PMID 32676121, 2020). "Moreover, this study uncovers a differential impact of NANOG and SOX2 expression on HNSCC prognosis, depending on tumor site and lymph node infiltration, which could facilitate high-risk patient stratification." (PMID 32635524, 2020). "Given the relevant role of SOX2 in tumorigenicity, here we used the SORE6 system to study whether those subpopulations showing SOX2/OCT4 transcriptional activity behave as bona-fide CSCs with higher tumor-initiating potential than other subpopulations." (PMID 32295077, 2020). "Tumor-promoting inflammation is an “enabling characteristic” of cancers, including ESCC, and to date, a number of important murine models for inflammation-mediated ESCC have been developed, including mice with Klf4 overexpression, p120 catenin knockout, or conditional Sox2 knockout." (PMID 30998758, 2019). "Because CyclinD1 inhibited Dicer expression by chromatin modifications, we further performed ChIP assays to determine whether altered CyclinD1 expression could also modulate the HP1α, H3K9me3 and SUV39H1 expression in the SOX2 and HOXA2 promoters in ICC and non-tumor HIBEpic cells." (PMID 31590696, 2019).